ENSG00000288093 (novel transcript)
Gene: Long non-coding RNA gene on chromosome 1 (161,399,998 to 161,401,868, forward strand). Ensembl gene ENSG00000288093.
Gene Ontology:
Molecular function: U4 snRNA binding
Biological process: formation of quadruple SL/U4/U5/U6 snRNP; spliceosomal tri-snRNP complex assembly
Cellular component: U4/U6 x U5 tri-snRNP complex; U6 snRNP